GSG1L2 (GSG1 like 2)
Tractability: Antibody: UniProt predicts a signal peptide or a membrane-spanning region; its Gene Ontology location is reachable by antibodies, with medium confidence.
Gene: Protein-coding gene on chromosome 17 (9,800,608 to 9,822,079, reverse strand). Ensembl gene ENSG00000214978.
Subcellular location: Membrane
Gene Ontology:
Cellular component: plasma membrane; membrane
Homologues: Orthologues: chimpanzee GSG1L2 (98% identical), macaque GSG1L2 (94% identical), pig GSG1L2 (76% identical), dog GSG1L2 (71% identical), mouse Gsg1l2 (68% identical), rat Gsg1l2 (67% identical), tropical clawed frog gsg1l2 (43% identical), zebrafish gsg1l2b (41% identical), zebrafish gsg1l2a (35% identical). Paralogues in human: GSG1L (42% identical), GSG1 (35% identical), PMP22 (15% identical), TMEM202 (14% identical), LIM2 (13% identical), CLDND2 (12% identical), EMP2 (11% identical), EMP1 (10% identical), EMP3 (10% identical), NKG7 (10% identical).